RNU6-1091P (RNA, U6 small nuclear 1091, pseudogene)
Gene: Small nuclear RNA gene on chromosome 7 (50,435,380 to 50,435,486, forward strand). Ensembl gene ENSG00000200815.
Homologues: Orthologues: chimpanzee U6 (100% identical), macaque U6 (91% identical), dog U6 (83% identical). Paralogues in human: RNU6-1287P (90% identical), RNU6-1340P (90% identical), RNU6-43P (90% identical), RNU6-727P (90% identical), RNU6-797P (90% identical), RNU6-175P (89% identical), RNU6-1175P (88% identical), RNU6-11P (88% identical), RNU6-15P (88% identical), RNU6-166P (88% identical), RNU6-199P (88% identical), RNU6-20P (88% identical), and 1288 more.